APOA1 (apolipoprotein A1)
Diseases named in the same sentence as APOA1 in open-access papers (continued):
Sharing a sentence is not in itself a finding about the gene and the disease.
diabetes (continued). "A large cohort-based study known as “INTERHEART” conducted across 52 countries identified several risk factors associated with MI, which include smoking, hypertension, abnormal lipid profile/blood lipoprotein (ApoB/ApoA1), and diabetes mellitus." (PMID 40270498, 2025). "These factors included blood glucose levels, ALP, ALT, GGT, total cholesterol, HDL, triglycerides, ApoA1, ApoB, sex, age, BMI, the length of illness, initial age of disease manifestation, marital condition, presence of diabetes, and hypertension." (PMID 40810071, 2025). "Duration of diabetes, smoking, hypertension, insulin use, and ApoA1/HDL-C ratio was significantly higher in the CAD group than in the group without CAD (p-values were < 0.001, < 0.001, 0.006, 0.001, and 0.004, respectively)." (PMID 38914982, 2024). "Univariate logistic regression revealed that diabetes, previous stroke, heart rate, WBC, ALT, FBG, cTnT, and Fg were risk factors for the high GS, ApoA1/ApoB, and PCSK6 rs1531817 CA + AA genotypes were protective factors against the occurrence of high GS." (PMID 39039525, 2024). "They demonstrated that the mean ApoA1 levels were lower in patients with diabetes compared to the healthy participants." (PMID 38914982, 2024). "It showed that an increase in the ApoA1/HDL-C ratio was associated with the incidence of diabetes and was a primary risk factor for diabetes in both genders." (PMID 38914982, 2024). "This study aimed to evaluate the correlation of serum HDL-c and apolipoprotein A1 (APOA1) with bone metabolism in Chinese postmenopausal women with type 2 diabetes mellitus (T2DM)." (PMID 37396919, 2023). "Further, after adjusting for hypertension, diabetes, CCBs, ACEI/ARB, and statins, serum APOA1 was still an associated factor for AF (OR = 0.269, 95% CI: 0.175–0.414, P < 0.001)." (PMID 37221493, 2023). "Our study revealed that both diabetic and cardiac diabetic patients have altered lipid profiles, ApoA1 levels, serum glucose, HOMA-IR, and total protein levels when compared to the control participants group." (PMID 37351102, 2023). "The apoB/apoA-1 ratio is more strongly related to CV risks than apoB in persons with pre-diabetes and metabolic syndrome often characterised by hypertriglyceridaemia." (PMID 34851955, 2021). "Tea drinking, higher education, sleep time >7 h/day, diabetes, and higher levels of (hemoglobin, low density lipoprotein, apolipoprotein A1, and serum calcium) are the protective factors for IA rupture." (PMID 33746870, 2021). "Abundant evidence has proven a higher predictive ability of the ApoB/ApoA1 ratio for CVDs, obesity, insulin resistance, and diabetes over conventional biomarkers." (PMID 32717783, 2020). "Gender distribution, prevalence of diabetes, levels of Apolipoprotein A1 (ApoA1) and high-density lipoprotein cholesterol (HDL-c), and the proportions of patients with ACS diagnoses were significantly different among the groups." (PMID 30984786, 2019). "Anti-apoA-1 autoantibodies have been found to be elevated in patients with Type 2 diabetes mellitus (T2D), though particularly only in those with CVD." (PMID 30744100, 2019). "Univariate analyses showed that gender, diabetes, Apolipoprotein A1 (ApoA1) and high-density lipoprotein cholesterol (HDL-c), and diagnosis of acute coronary syndrome (ACS) were associated with plaque vulnerability (P all < 0.05)." (PMID 30984786, 2019). "CVD risk factors were extracted and further analysed with conditional logistic regression models for association with subsequent RA development, including hypertension, apolipoprotein (Apo)B/ApoA1 ratio, BMI, diabetes and smoking habits." (PMID 28666478, 2017). "The nature of ApoA1 as a covariate of inflammatory markers and a determinant in the metabolic syndrome (diabetes and prehypertension) was unexpected and further suggests its reconversion in an inflammatory apolipoprotein." (PMID 25849372, 2015).
diabetes (continued). "Variables in this model included the age, gender, smoking, diabetes, ventricular function, NT-proBNP, ApoA1, HDL-C, and fasting blood glucose." (PMID 26257459, 2015). "Further analysis showed significant relationships between changesin APOA-1 and changes in triglyceride, total cholesterol, and body mass index after controlling for age, gender and family history of diabetes." (PMID 24710015, 2014). "For univariate analysis in this study, ApoA1/ HDL, ApoB/LDL, ApoB/ApoA1, and LDL/HDL were separately and significantly associated with diabetes." (PMID 24093822, 2013). "The adjusted OR for the top ApoA1/HDL-C tertile remained significant and was independently associated with diabetes in Model 8, at OR of 2.24 (P-trend =0.028)." (PMID 24093822, 2013). "The top ApoA1/HDL-C tertile was significantly and independently associated with diabetes at ORs of 2.98 (P-trend = 0.030) for men and 2.15 (P-trend = 0.047) for women." (PMID 24093822, 2013). "In conclusion, ApoA1/HDL-C was highly associated with diabetes and was superior to ApoB/LDL-C, ApoA1, ApoB, LDL-C/HDL-C, ApoB/ApoA1, LDL-C, HDL-C, and TG among the general Taiwanese population." (PMID 24093822, 2013). "Overall, low income level, history of hypertension, history of diabetes, and ApoB/ApoA1 ratio were more frequent in cases than in controls (P < 0.05 for all comparisons)." (PMID 22245707, 2012). "The final logistic model for presence of obesity included age, sex, diastolic blood pressure, diabetes, homocysteine, insulin resistance, apoA1, and apoB." (PMID 21159217, 2011). "Serum FGF-21 levels correlated positively with triglycerides, fasting blood glucose, apolipoprotein B100, insulin and HOMA-IR but negatively with HDL-C and apolipoprotein A1 after adjusting for BMI, diabetes and hypertension." (PMID 21206918, 2010). "Independent risk factors at age 50 for death due to acute MI before the 70-year examination were high BMI, high DBP, high ApoB/ApoA1 ratio, T wave abnormalities, smoking and diabetes mellitus." (PMID 16519804, 2006). "Significant differences were observed between the simple heart failure (SHF) group and the CRS group in terms of age, history of diabetes mellitus, levels of triglycerides (TG), apolipoprotein A1 (apo-A1), apolipoprotein B (apo-B), ApoB/ApoA1 ratio, and serum creatinine (Scr)." (PMID 41908053, 2026). "Adjustment for the apoB/apoA-1 ratio did not affect this association among those with diabetes and only slightly attenuated the association for those with IFG and high glucose." (PMID 39915078, 2025). "Rates of pre-diabetes, T2D, dyslipidemia, hyperuricemia, and high-risk fasting serum Apolipoprotein B to Apolipoprotein A1 Ratios were comparable across participants, but not hypertriglyceridemia and hypertension." (PMID 39075463, 2024). "Notably, smoking history and diabetes mellitus were shown to exert a significant impact on the severity of CHD independently of the ApoB100/ApoA1 ratio." (PMID 38393015, 2024). "This study investigated the association between ApoA1/HDL-C ratio and CAD in patients with T2D, aiming to clarify whether this ratio has predictive value for CAD in diabetes." (PMID 38914982, 2024). "Diabetes, smoking history, uric acid, and ApoA1 independently predict the occurrence of MACE." (PMID 38805487, 2024). "It should be mentioned that according to clinical guidelines, a large number of the patients with diabetes were probably treated with statins, which may raise apolipoprotein A1 and lower apolipoprotein B." (PMID 38084202, 2023). "ApoA1 is the most abundant apolipoprotein contained in HDL, but there are other apolipoproteins in HDL that have been reported to associate with various diseases, such as diabetes, dementia, and cancers." (PMID 36732570, 2023). "These modifiable risk factors include hypertension, diabetes, smoking, abdominal obesity, psychological index, lack of exercise, lack of fruits and vegetables, apolipoprotein B/apolipoprotein A1 (ApoB/ApoA1) ratio, and the use of alcohol." (PMID 35812625, 2022).
diabetes (continued). "The higher ApoB/ApoA1 ratio seen in our study of patients in late CKD compared to early CKD, is relevant given the magnified cardiovascular risk associated with progressive diabetes-associated CKD." (PMID 35295919, 2022). "Furthermore, we also showed that the Lp-PLA2 concentration was definitely correlated with apoB and apoB/apoA1 after adjustment for hypertension, age, gender, smoking, and diabetes mellitus." (PMID 33029257, 2020). "After adjustment for several risk factors regarding CAD, like hypertension, gender, smoking, age, and diabetes mellitus, there had still been positive associations between the Lp-PLA2 concentration and apoB (β = 0.364, P < 0.001) as well as apoB/apoA1 (β = 0.390, P < 0.001)." (PMID 33029257, 2020). "The selected features of the proposed classifier on the Set 1 were CETP TaqIB [rs708272], CETP A373P [rs5880], LPL D9N [rs1801177], ApoE, ABCAI R1587K [rs2230808], APOA5 C-1131T [rs662799], LPL HindIII [rs320], APOC3 SstI [rs5128], family history of obesity, and diabetes, and APOA1 MspI [rs2893157]." (PMID 30026888, 2018). "On the other hand, it has been described that apolipoprotein A1 (apo-A1), a key factor for the intraretinal lipids transport and a potent scavenger of reactive oxygen species, is overexpressed in all the neuroretinal layers in persons with diabetes." (PMID 28238189, 2017). "Insulin sensitivity in clamp studies was independently associated with serum bicarbonate and apolipoprotein A1: apolipoprotein B ratio in a sample of CKD patients without diabetes." (PMID 27716263, 2016). "In addition, apolipoprotein A1 increased (with the exception of patients with diabetes receiving placebo-etanercept) and adiponectin increased slightly through week 24; leptin and apolipoprotein B did not change." (PMID 27704313, 2016). "However, animals with marked hyperglycaemia and severe diabetes showed higher serum APOA1 concentration suggesting a positive regulation in vivo." (PMID 24468233, 2014). "The minor allele of APOA1 rs670 has been correlated to altered HDL-C, diabetes and coronary-artery disease: lower levels of HDL-C was observed in Northern Indians, and correlated with severe forms of cardiovascular diseases in Northern Indians, Caucasians in Spain and Australia." (PMID 23829168, 2013). "Moreover, current literature suggests an association between the ApoA1/HDL-C ratio and diabetes." (PMID 38914982, 2024). "Finally, the use of both cholesterol (3.27% vs. 8.82%, with p < 0.001 for HDL, <5% vs. <8% with p = 0.012 for the apoA1 group) and diabetes (4.23% vs. 8.82% with p < 0.001 for the HDL group, and 6.38% vs. 12.05% with p = 0.012 for the apoA1 group) drugs increased the risk of severe COVID-19." (PMID 37372137, 2023). "In addition, complicated diabetes was negatively associated with infection for the HDL group (16% vs. 15%, p < 0.001), while uncomplicated diabetes was positively associated with infection in both groups (26.1% vs. 26.5% for the HDL group, and 28% vs. 36% for the apoA1 group; both p < 0.001)." (PMID 37372137, 2023). "The association between ApoB/ApoA1 ratio and Lipoprotein (Total Cholesterol/HDL-c) ratio, modified Gensini score and Framingham risk score were compared using multivariate linear regression analysis after adjustment for age, sex, BMI, smoking, drinking, hypertension and diabetes." (PMID 31744496, 2019). "Covariates included age, sex, lipoprotein(a) level [Lp(a)], apolipoprotein A1 level (Apo A1), alanine aminotransferase (ALT) level, neutrophil count (NEUT), hypertension status, diabetes status, smoking status, and alcohol consumption status." (PMID 41647510, 2026). "The conclusions are as follows: 1) Statistically significant differences were observed among the two groups in terms of gender, hypertension, age, duration of diabetes mellitus, plaque location, TG, TC, Apo A1, VLDL, VLDL/ApoB, HDL/ApoA1 (P<0.05)." (PMID 41403409, 2025).
diabetes (continued). "Age, sex, hypertension status, diabetes, ALT, FBG, TC, LDL, TC/HDL, ApoB, ApoA1/ApoB, cTnT, Fg, and PCSK6rs1531817 genotypes were the variables tested in the comparison among patients with single vessel disease (SVD), DVD, and TVD." (PMID 39039525, 2024). "The univariate analysis indicated a significant correlation between lumbar BMD, β-CTX, and other factors including age, BMI, triglycerides, ALT, UA, diabetes, hypertension, monocyte, hemoglobin, platelet, and PTH, particularly with APOA1." (PMID 39144661, 2024). "Baseline characteristics of these patients included mean age 59 years, male sex (81%), diabetes (33%); and mean body mass index 28.3 kg/m2, LDL-C 2.1 mmol/L, lipoprotein(a) 2.9 mg/dL, and apolipoprotein A1 13 mg/dL." (PMID 37328736, 2023). "The positive correlation noted in this study between CSF ApoA1 and CSF inflammation markers of AGE-RAGE signaling pathway in diabetes is also consistent with this." (PMID 36927447, 2023). "Baseline characteristics of these patients included mean age 59 years, male sex (81%), diabetes (33%); and mean body mass index 27.3 kg/m2, LDL-C 2.0 mmol/L, lipoprotein(a) 2 mg/dL, and apolipoprotein A1 13 mg/dL." (PMID 37328736, 2023). "ROC analysis was used to identify cut-off values of ApoA1, IL-10 and TNF-α in diabetes patients with foot ulcers." (PMID 35836916, 2022). "Also, triglyceride, serum ApoB, and serum ApoA1 levels did not improve, which is of interest, because all 3 of these parameters are mentioned as risk factors for developing posttransplant diabetes mellitus." (PMID 36593877, 2022). "We first included the following variables in the model: age, sex, education level, smoking and drinking history, diabetes duration, insulin use, BMI, HbA1c, FBG, PBG, HDL-C, LDL-C, TC, TG, ApoA1, ApoB, sLPR1, and the LRP1 genotype." (PMID 33013281, 2020). "Smoking, diabetes, hypertension, manual work, and fewer than nine years of education were more common, while body mass index, TC, TG, LDL, apoB, and the ratio apoB/apoA-1 and glucose levels were higher, among CV cases than controls." (PMID 30138379, 2018). "We suggest that the imbalance between ApoA1 and HDL-C serum levels was more critical in the pathogenesis of diabetes." (PMID 24093822, 2013). "In the fully adjusted model, which included age, gender, smoking, hypertension, diabetes, CKD, ApoA1, ApoB, albumin, uric acid, eGFR, fibrinogen, LVEF, and Gensini score, Lp(a) remained linearly and positively associated with all-cause and cardiovascular mortality (P-nonlinear = 0.528 and 0.859)." (PMID 40496568, 2025). "Furthermore, APOB/APOA1 can be used for the prediction of CAVD, and the combination of APOB/APOA1 with age, history of diabetes, DBP, Cys-c, and NLR has better prediction performance for CAVD." (PMID 40787622, 2025). "Using direct measures of IR via steady-state plasma glucose (SSPG) concentration during the insulin suppression test, we characterized the ApoA1 proteome in a cohort of individuals without diabetes and assessed the effects of PIO and WL interventions." (PMID 41226726, 2025). "It was demonstrated that hyperglycemia causes glycation of the ApoA-1 molecule of HDL particles, leading to an increase in its degradation three times faster than in a person without diabetes." (PMID 39120243, 2024). "A case-control study compared the ApoA1 levels in patients with diabetes and non-diabetic healthy individuals." (PMID 38914982, 2024). "It is worth mentioning that the level of ApoA1 is more stable than the level of blood lipids, especially in the group of diabetes patients, and its level will not be significantly affected by the pre meal state." (PMID 39033211, 2024). "Moreover, plasma taurine levels showed a positive correlation with apolipoprotein A1 (APO A-I) (R = 0.29, p = 0.043) in PCC patients with diabetes, which illustrates a potential role for taurine in lipid metabolism and cholesterol balance." (PMID 38837993, 2024).
diabetes (continued). "Furthermore, ApoA1 plasma concentration was decreased, whereas ApoC1 and ApoH were increased in the patients with CAD and/or diabetes." (PMID 37686357, 2023). "The use of diabetes drugs reduced the risk of AKI by 8% (OR = 0.92, p = 0.01) in the HDL group, although it was not statistically significant for the apoA1 group (OR = 1.00, p = 0.33)." (PMID 37372137, 2023). "The effects of gender, diabetes duration, non-high-density lipoprotein cholesterol, apolipoprotein A1, lipoprotein (a), homocysteine, atherogenic index of plasma (AIP), nerve conduction velocity, and carotid plaque merit further study." (PMID 36440044, 2022). "These support a close relationship between serum lipids and lipoprotein except for HDL-c, ApoA1, or Lp-a and LFC in overweight/obesity, with similar patterns in diabetes except for LDL-c and FFA, but show lost correlations between lipid markers and lean/normal weight phenotypes." (PMID 34899591, 2021). "The differences in age, sex, diabetes, smoking, drinking, BMI, WBC, TC, and LDL-C in the CHD group were not statistically significant (P > 0.05), but the differences in hypertension, TG, HDL-C, ApoA1, and CRP levels were statistically significant (P < 0.001)." (PMID 34235188, 2021). "MoCA score was considered the dependent variable, and age, sex, education level, diabetes duration, insulin use, BMI, HbA1c, FBG, PBG, TC, TG, LDL-C, HDL-C, ApoA1, ApoB, and sLRP1 were considered the independent variables in the multiple linear regression analysis." (PMID 33013281, 2020). "In our study, we also find an increased ratio of apoB: apoA1 value was a highly significant risk factor of CAD independent of smoking, hypertension, and diabetes." (PMID 30134981, 2018). "Mean apoA1 values were virtually identical in our study community, regardless of diabetes status, but mean HDL cholesterol levels were significantly lower in participants with diabetes." (PMID 21159217, 2011). "The fasting blood glucose (GLU), total cholesterol(TC), triglyceride (TG), low-density lipoprotein cholesterol(LDL-C), non-high-density lipoprotein cholesterol (nonHDL-C), apolipoprotein A-1 (ApoA-1), and apolipoproteinB (ApoB) levels, as well as diabetes rates, were lower (P=0.01)." (PMID 41821770, 2026). "Patients were stratified into APOA1 quartiles (0.29–1.05, 1.06–1.19, 1.20–1.34, and 1.35–2.49 ng/mL), and interquartile differences within lumbar BMD, β-CTX, age, BMI, triglycerides, ALT, UA, diabetes, hypertension, monocyte, hemoglobin, platelet, PTH, HDL, LDL, neutrophil and FAR." (PMID 39144661, 2024). "Therefore, the ApoA1/HDL-C ratio may better represent HDL-C structure and function and better predict CVD in patients with diabetes." (PMID 38914982, 2024). "In patients with non-alcoholic fatty liver disease (NAFLD) with or without type 2 diabetes mellitus (T2DM), alpha-2 macroglobulin (A2M), apolipoprotein A1 (ApoA1), and haptoglobin are associated with the risk of liver fibrosis, inflammation (NASH), and COVID-19." (PMID 35327501, 2022). "The expression of APOA1 in control pancreas and severe down-regulation in pancreas with T2D is very novel and important finding, which open new avenues on lipid metabolism, HDL, cardiovascular events, diabetes and its complications such as neuropathies, and will help to design new future studies." (PMID 26337083, 2015). "The apoB:apoA1 ratio was found to predict metabolic syndrome in nonobese but not obese participants, perhaps because obese participants are more likely to have diabetes." (PMID 21159217, 2011). "So, In this study, plasma levels of apoA1 and apoB were compared in diabetic children with type I diabetes mellitus (DM), healthy children with nondiabetic parents (HNDPs), and healthy children with diabetic parents (HDPs)." (PMID 22811893, 2012).